CD24 (CD24 molecule)
Diseases named in the same sentence as CD24 in open-access papers (continued):
Sharing a sentence is not in itself a finding about the gene and the disease.
tumor (continued). "By day 9, all vehicle-treated SK-N-AS/CD24 tumors had breached a tumor size of 2,000 mm3 and were unenrolled, whereas none of the vehicle-treated VO or WT tumors had done so." (PMID 38214542, 2024). "Moreover, CQ increased the sensitivity to PTX and reduced lung metastases, tumor growth, and recurrence in orthotopic murine MDAMB231 and SUM159PT tumor models and diminished the CD44+/CD24−/low CSC population in a clinical trial." (PMID 38256019, 2024). "This study revealed that whereas the rate of tumor growth for the vehicle-treated VO and WT tumors was not significantly different, the vehicle-treated SK-N-AS/CD24 tumors grew at a considerably faster pace." (PMID 38214542, 2024). "Recent studies have elucidated the presence of a CD133+/CD24+ cell subpopulation in ccRCC, which promotes angiogenesis within the TME and contributes to resistance against multitarget tyrosine kinase inhibitors, leading to tumor progression and poor prognosis." (PMID 38928496, 2024). "Similar to IMR-32, the expression of CD24 did not reveal any significant variation between the in vitro (cells) and in vivo (tumor) samples." (PMID 38214542, 2024). "CD24 and CD44 have been regarded as negative prognostic factors for MSGTs, associated with increased tumor size, positive lymph nodes, and advanced clinical stage." (PMID 39858584, 2024). "CD24, a glycosylphosphatidylinositol (GPI)-anchored protein, is expressed on the membranes of cancerous cells, as well as in the cytoplasm and nuclei of some cancerous cells, such as tissue and tumor stem cells." (PMID 38279998, 2024). "The highly expressed inhibitory receptor Siglec-10 on TAMs interacts with the new “don't eat me” signaling molecule CD24, activates the SHP-1/SHP-2-mediated inhibitory signaling pathway, and inhibits the phagocytosis of tumor cells by macrophages, thereby exerting an immune escape effect." (PMID 38725856, 2024). "Therefore, the inhibition of CD24 and CD47 has become a new strategy of anti-tumor immunotherapies and has prompted great research potential in recent years." (PMID 38787372, 2024). "Other genes: BTG1, CD24, KRT19, RAC2 and RGS1 were significantly upregulated in tumour samples." (PMID 39098994, 2024). "Surprisingly, this dramatic enhancement in the rate of tumor growth offered no advantage to SK-N-AS/CD24 ZIKV-treated tumors in their resistance to viral killing." (PMID 38214542, 2024). "Furthermore, the protein level of CD74 expression was found to be expressed along with ALDH compared to the moderate expression level of CD24 and CD44 in the PDX tumor models." (PMID 39056676, 2024). "We identified a negative correlation between tumor cells that were non-stem by CD44/CD24 but stem by CD133 and those that were CD44+CD24−CD133− in EpCAM-negative CTCs (r = −0.69, p = 0.024)." (PMID 39456890, 2024). "Additionally, the proportion of CD24, EpCAM, CD13, or CD133 positive cells were reduced in SCARB2 knockout tumor organoids." (PMID 37739936, 2023). "The pan-tumor panel identified nine tumor cell subsets, which were defined as being negative for CD45 and CD56, but expressing at least one of the three markers, namely, EpCAM, FOLR1, and CD24." (PMID 37894472, 2023). "Therefore, we would like to explore the spatial relationship between CD79A+CD24-PANCK+-BCSCs subpopulation and CD8+ T cells with FOXP3+ or not to reveal the influence of CD79A+CD24-PANCK+-BCSCs subpopulation on CD8+T cells and tumor microenvironment." (PMID 38066053, 2023). "Additionally, CD24 regulates key factors like STAT3 and tissue factor pathway inhibitor-2 (TFPI-2), influencing tumor metastasis by affecting their expression and activity." (PMID 38313430, 2023). "This study evaluates the anti-tumor mechanism of IMM47, a humanized anti-CD24 mAb." (PMID 37846296, 2023). "The presence of disseminating tumour cells that express EpCAM but not CD24 did not correlate with metastasis." (PMID 37975646, 2023).
tumor (continued). "Overall, the CD44/CD24 cell distribution in TNBC cells was significantly altered across the surface topographies examined, strengthening the importance of mechanical stimuli in modulating tumor stemness cell ratios." (PMID 36968199, 2023). "The expression of NOS2 in CD24 + CD133 + liver CSC promotes NO/cGMP/PKG, driving Notch signaling and stemness characteristics in vitro and in vivo, and accelerates HCC initiation and tumor formation in the murine HCC tumor." (PMID 37958916, 2023). "Moreover, the depletion of miR-31 in MMTV-PyVT mice led to compromised tumor growth, a reduced number of cancer stem cells (CD24+/CD90+), decreased tumor-initiating ability and impaired metastasis to the lung." (PMID 37374142, 2023). "Notably, TIPARP was highly expressed in the tumor relative to the normal group expression, and CD24, TACC1, HSD17B10, and CAV1 were less expressed in the tumor relative to the normal group." (PMID 37907864, 2023). "Other histopathological characteristics of the tumor, such as perineural invasion, did not affect the percentage of PBLs expressing CD24+/CD11b− in flow cytometry." (PMID 38138858, 2023). "Additionally, CD24 is capable of initiating ERK and p38MAPK activation, which stimulates the proliferation of tumor cells in both controlled lab environments and living beings." (PMID 38313430, 2023). "In one experiment, an injection of CD24-positive cells triggered the formation of tumour xenografts in nude mice, while an injection of the same amount of CD24-negative cells failed to trigger this effect." (PMID 38201468, 2023). "In addition, conditionally overexpressing KLF10 in MiaPaCa cells revealed that the levels of CD47, CD24, and CD44 expression on tumor cells were reduced by more than 50%." (PMID 37308977, 2023). "Compared to the miR-135b-5p-low group, higher expression of CD24, C-MYC, and NANOG was observed in the miR-135b-5p-high group within stem-like or malignant cell clusters, suggesting more remarkable stemness properties of tumor cells in this group." (PMID 36755690, 2023). "The density of tumour-resident CD103+ CD11b− cDC1s but not CD24+ total DCs was negatively correlated with the tumour weight in all tumour-bearing mice, suggesting the cDC1s played a critical role in combatting the tumour growth." (PMID 37433774, 2023). "CD24 and CD47 are both expressed abnormally on tumor cells and express in normal tissues." (PMID 37484024, 2023). "Targeting the “do not eat me” signals CD47 and CD24 with an antibody or Fc-fusion proteins increases the macrophage phagocytosis of tumor cells and enhances antitumor immunity." (PMID 38016957, 2023). "CD24 could inhibit the tissue factor pathway inhibitor-2 (TFPI-2) by regulating the Src related pathway, and then promote the metastasis of tumor cells." (PMID 37359556, 2023). "Furthermore, an in-depth analysis of phenotypic characteristics of β4+ tumor cells revealed a significantly increased proportion of E-cadherin+ and CD44+CD24- cells in patients with liver metastases compared to patients with lung or no distant metastases." (PMID 36769251, 2023). "When CD24-Fc administration lagged several days behind initial vaccination, vaccine efficacy was not altered and treatment resulted in excellent tumor free survival." (PMID 37346042, 2023). "Two of these tumor cell populations expressed EpCAM, FOLR1, and CD24 simultaneously." (PMID 37894472, 2023). "Our results showed that TGFβRI and GSK3β are located upstream of NDRG1 in the signaling pathway and demonstrated that a combination of TGFβ and GSK3β inhibitors has the potential to reduce TNBC progression by impairing tumor initiation and ALDH1+ and CD44high/CD24- populations of CSCs." (PMID 36594086, 2023). "In addition, CD24, similar to CD47 and PD-L1 checkpoints, can reverse the function of immune cells, resulting in overall pro-tumour progression." (PMID 38137380, 2023).
tumor (continued). "Notably, the immune checkpoint molecules CD24 and CD200 have garnered attention owing to their involvement in tumor immune evasion." (PMID 37894750, 2023). "We also show that EpCAM+Vim+CD24- tumour cells in the stroma do not correlate with metastasis, and therefore the clinically predictive utility of tumour cell staining in the stroma can be isolated specifically to the EpCAM+Vim+CD24+ EMT CSCs." (PMID 37975646, 2023). "The tumor/stromal cells included one CD56+fibroblast population and nine CD45−CD56−cell populations, which were distinguished by the expression of the three select tumor markers, namely, EpCAM, FOLR1, and CD24." (PMID 37894472, 2023). "For instance, GBC9-MT showed elevated expression of CD24 (immune checkpoint in promoting immune evasion) and IGFBP2 (metabolic checkpoint in promoting tumor growth), and GBC10-MT displayed cancer stem cell signature (OLFM4) and enhanced cell migration (e.g., CLDN3, CEACAM5)." (PMID 36198671, 2022). "Interestingly, epithelial-like BCSCs expressing the BCSC marker ALDH are more proliferative and are located at central areas of the tumour, whereas CD44+CD24− mesenchymal-like BCSCs are more quiescent and located at the invasive front of the tumour." (PMID 35326385, 2022). "To further explore whether the system could sustain stemness, we examined if continuous culturing of the tumour spheroid with our P-GRGD+NW system will sustain and maintain the stemness using CD24 as the representative marker." (PMID 36612229, 2022). "Surprisingly, both CD24 and CD47, two classic ligands of “don’t eat me” signal, were notably upregulated on tumor cells from mice received anti-CD20 antibody, whereas comparable expression levels of their receptors were observed on macrophages, Siglec-10 and SIRPα, respectively (Data not shown)." (PMID 36249034, 2022). "Further measuring the markers related to the tumor formation ability in mice subcutaneous tumors, we found that EpCAM, CD13, CD24, CD44, CD90 and CD133 in ZNF334-OE cells was significantly lower than that of the control group, which was consistent to the phenotype of the mice model." (PMID 35534462, 2022). "Here, CD24+CD38+ Bregs promote tumour progression through a mechanism involving CD40 and CD40L interactions with cancer cells that subsequently leads to the secretion of IL-10 and TGFβ that sustain tumour proliferation." (PMID 35350071, 2022). "CD24 represents a target of the transcription factor hypoxia inducible factor-1α (HIF-1α), a molecule commonly upregulated in hypoxic conditions, including during primary tumor growth and metastasis." (PMID 36013184, 2022). "Flow cytometry analysis of mammary glands showed a significant decrease (P = 0.027) in CD24+CD29high basal epithelial cells in TGFBRi-treated animals that did not develop tumors relative to control tumor-bearing animals." (PMID 36476730, 2022). "As few as 100 cells with this phenotype had the ability to form tumours in mice, comprising phenotypically diverse mixed populations of nontumorigenic cells present in the initial tumour as well as additional CD44+/CD24− tumorigenic cells." (PMID 36077812, 2022). "Although tumor-associated macrophages could not be directly assessed due to lack of material, Siglec-10 expression on healthy donor-derived macrophages was significantly increased upon direct-cell-cell contact with CD24+ cells in co-cultures between CD24-expressing MCL cells." (PMID 35625912, 2022). "In addition, a change in CD24 expression, as observed in our study, is known to be indicative of a cancer stem cell shift able to promote EMT and tumor progression." (PMID 36552039, 2022). "In addition, CD24, which is highly expressed in Cancer Cells, synergizes with SIGLEC10 in Dendritic Cells, Macrophages, GMP Cells, B Cells, and Mast Cells to mediate tumor immune escape." (PMID 36401283, 2022).
tumor (continued). "Although there were no statistical differences in the mean number of these non‐tumor immune cells between CD24‐high and CD24‐low groups, only a few TME cells were observed in CD24‐positive DLBCL." (PMID 35289116, 2022). "Similarly, we observed that the cells in cluster 16 and 30 were all derived from non-tumor liver and highly expressed in GPC3 and CD24; thus, they were annotated as hepatocytes." (PMID 36605219, 2022). "The paradigm of early metastasis with a consistent proportion of primary tumor cells enriched with high CD44, and low CD24 (high CD44/low CD24) stem cell-like features carries the potential to migrate primary tumor sites and form metastatic colonies in distant sites." (PMID 35736645, 2022). "The CD24-expressing tumor stem cells did not home to the metastases in the lymph nodes, whereas CD276-expressing cells were found in the metastases." (PMID 35563359, 2022). "The inability of tumor cells to repress CD24 and the wider expression of HMGA2 during the differentiation process may favor in vivo tumor growth." (PMID 35884847, 2022). "There was a significant association between CD44+/CD24 low/− expression and the ability of the tumor to metastasize, as the expression of CD44+/CD24 low/− in patients with distant metastasis was 61% (range: 7–80%), compared to 25.3% (range: 0.1–68%) in those who had not metastasize (P = 0.038)." (PMID 36585652, 2022). "The CD24 molecule may also regulate NANOG and OCT4 expression, thus stimulating tumor growth and resistance to chemotherapy." (PMID 35269636, 2022). "Normal and tumour tissues from such patients were analysed by qRT-PCR for the following 12 genes; six from RNA-seq: CLDN1, MAGEB2, CD24, CEACAM6, IL1B and ISG15 and six from RNA-seq and proteomics cross-linking: AKR1C3, TNFAIP2, RAB7A, LGALS3BP, PSCA and SSRP1." (PMID 36428603, 2022). "Since the discovery of the first tumor phagocytosis-related checkpoint, namely the CD47/SIRPα axis, in the late 2000s, other tumor phagocytosis-related checkpoints have been identified: the PD-1/PD-L1 axis, MHC-I/LILRB1 axis, and CD24/SIGLEC-10 axis." (PMID 35978372, 2022). "However, we analyzed the expression level of CD24 in normal oral mucosal tissues and primary OSCC tumor tissues from the TCGA dataset." (PMID 36498950, 2022). "Therefore, in this study, we isolated CD24−/low/CD44+ cells from RT-R-MDA-MB-231 cells and determined the role of these CSCs in RT-R-TNBC on tumor progression and immune evasion." (PMID 34502547, 2021). "CD24 gene deletion in tumor cell lines or mAb-mediated blockade has been reported to enhance the phagocytosis of MCF-7 cancer cells in vitro, and MCF-7 tumor growth has been suppressed in vivo in CD24−/− mice." (PMID 34638388, 2021). "In addition, BCSCs expressing both CD24- CD44+ and ALDH+ are recognized as highly purified BCSCs, exhibiting the greatest tumor-initiating capacity." (PMID 34801088, 2021). "Emerging evidence suggests that PaCSCs, marked by CD44, CD24, ESA, CD133, or c-Met proteins, characterize a subset of PDAC with distinct stemness features that permit them to drive tumor heterogeneity, metastasis and resistance to the current chemotherapy and radiation." (PMID 35186942, 2021). "Compared with the unconverted CD44-/CD24- tumor cells, PPME1, RHBDL2 and HIST1H4H mRNA transcripts increased in the newly converted CD44+/CD24- CSCs with a change of >two folds, which were similar to that in parental CD44+/CD24- CSCs." (PMID 34318746, 2021). "Concordantly, GSI treatment reduced mammosphere formation and tumour growth from CD44+/CD24low cells but not CD44+/CD24– cells." (PMID 34295896, 2021).
tumor (continued). "The stem cell marker, CD24 showed no staining in non-tumour tissue and strong staining in all cells of the tumour tissue, while CD44 showed < 10% stained cells in non-tumour tissue and strong staining in most cells of the tumour tissue." (PMID 33906633, 2021). "However, to exclude the effects of CSCs, patients in the C1 group also had a higher risk to develop delayed distant metastasis during 5–7 years post tumor resection than those with <2% of CD44+/CD24- CSCs and < 19.5% of CD44-/CD24- tumor cells (the C0 group)." (PMID 34318746, 2021). "Moreover, we were able to identify a segregated tumor cell cluster with co-expression of GD2, CD56, B7-H3, CD24 and FAIM2 (orange cluster)." (PMID 34503120, 2021). "Furthermore, TGFβ inhibitor significantly retarded tumour formation, while reducing cell migration and invasion abilities, tumour mass, and the number of metastatic foci derived from orthotopically implanted ALDH+ CD44+ CXCR4+ CD24+ subpopulation." (PMID 34247196, 2021). "Similarly, CD44+/CD24− CSCs were present at low frequency in TUBO tumours and slightly increased in BALB-neuT tumours, while they were abundant in both 4T1 and TS/A tumours, in agreement with the results obtained in vitro." (PMID 33257841, 2021). "Then, we examined the properties of CD24−/low/CD44+ cells related to tumor progression by comparing MDA-MB-231 cells and RT-R-MDA-MB-231 cells harboring different proportions of CD24−/low/CD44+ cells with the CD24−/low/CD44+ cells isolated from RT-R-MDA-MB-231 cells." (PMID 34502547, 2021). "Taken together these studies indicate that increased PGE2/EP4 signaling promote the tumor and mesenchymal activities of CD44+/CD24- breast CSCs; however, any corresponding effect on the more epithelial-like ALDH+ CSCs was not specifically assessed in the studies." (PMID 35127497, 2021). "Furthermore, analysis of metastatic dynamics revealed that patients with a higher frequency (≥2%) of CD44+/CD24- CSCs usually developed distant metastasis earlier than those with < 2% of CD44+/CD24- and >19.5% of CD44-/CD24- tumor cells (the C1 group)." (PMID 34318746, 2021). "CD24- CD44+ BCSCs are localized at the tumor invasive edge, staying quiescent with highly invasive characteristics while ALDH+ BCSCs are located at the center of tumor with highly proliferative characteristics." (PMID 34801088, 2021). "CD24/CD44 analysis showed coordinated downregulation of CD24 and upregulation of CD44 in CTCs in the BM18 and LuCaP105 PDX models in comparison with their tumours." (PMID 34206049, 2021). "Six-week-old female BALB/c nude mice were injected subcutaneously with MDA-MB-231, RT-R-MDA-MB-231, and CD24−/low/CD44+ cells, and tumor volumes and body weights were measured three times weekly beginning on the 7th day after injection, as described in the Materials and Methods section." (PMID 34502547, 2021). "In order to better characterize these two cell populations, an additional FACs panel including a tumor marker (EpCAM), stem cell markers (CD44, CD24, and CD133) and mesenchymal‐like and mesothelial cell markers (CD90, podoplanin and mesothelin) was established." (PMID 34060699, 2021). "To some extent, we speculated SLC27A6 promoted NPC metastasis via increasing CD24 and CD44 positive tumor stem cells." (PMID 35047398, 2021). "Of note, we observed nuclear CD24 staining in iSOX11 tumour cells, but not in iEV, niEV, or niSOX11 tumours, in line with the observed in vitro result." (PMID 32909943, 2020). "CD24: The sialoglycoprotein CD24 is expressed on the surface of cells, constitutes a prevalent CSC marker, has roles in cell signaling and has recently been demonstrated to promote tumor immune evasion." (PMID 32194856, 2020). "For example, studies in pancreatic cancer identified a slow-cycling population, enriched for the CSC markers CD24+/CD44+, CD133+ and ALDH, which also had enhanced chemotherapeutic resistance and could recreate the initial heterogeneous tumor cell population." (PMID 32194856, 2020).